IL6 (interleukin 6)
Diseases named in the same sentence as IL6 in open-access papers (continued):
Sharing a sentence is not in itself a finding about the gene and the disease.
COVID-19 (continued). "Similarly, it has been reported that TNF-α, IFN-γ, IL-2, IL-4, IL-6, and IL-10 are also highly expressed in the plasma of COVID-19 patients; moreover, IL-6 and IL-10 are significantly increased in the serum of patients with critical conditions, compared to the moderate ones." (PMID 36422642, 2022). "Moreover, IL-6 level was a good predictor for the progression and severity of COVID-19." (PMID 36675695, 2022). "In critically ill COVID-19 patients, several factors may favor aspergillosis development, including inflammatory pulmonary damage and immunosuppressive drugs used to treat the disease, especially anti-IL-6 drugs." (PMID 35205914, 2022). "In particular, IL-6 might be a promising biomarker for severity and therapeutic decision-making, as antagonizing the IL-6 directly or through the JAK-STAT pathway has demonstrated improved prognosis in hospitalised COVID-19 patients with hypoxia and systemic inflammation." (PMID 35353232, 2022). "Our study of COVID-19 patients’ lung biopsies validated a correlation between the macrophages and the disease, showing a heavy infiltration of pro-inflammatory macrophages in tissue samples from distal lung regions with high levels of inflammatory cytokine IL-6 in severe cases." (PMID 35440562, 2022). "In the plasma of COVID-19 patients, the infection-related elevation of IL-6 and IL-6R results in a boost of endothelial cells and TF and this infection-induced coagulopathy may play a pivotal role in thrombocytopenia, while the cytokine storm triggers the thrombocytosis." (PMID 36295093, 2022). "Although no studies were reported before the specifical findings regarding the inflammatory markers in patients of the Roma population with severe COVID-19, it was previously discussed how IL-6 levels could indicate a persistent lung injury in patients with SARS-CoV-2 infection." (PMID 36431254, 2022). "Interleukin-6 is believed to play a pivotal role in the cytokine release syndrome and systemic inflammation and coagulation in severe COVID-19 patients and IL-6 receptor blockade by immune-modulatory agent; i.e., tocilizumab has gained popularity in the treatment of COVID-19." (PMID 36013543, 2022). "A major problem with COVID-19 has been the inability to predict which patients could develop a severe disease and the most accurate method to predict the outcome of the infection has been the measurement of interleukin-6 (IL-6)." (PMID 36466830, 2022). "Furthermore, genetic host traits such as IL-6 gene polymorphisms, which might contribute to SARS-CoV-2 susceptibility and RA, are similar in COVID-19 and RA." (PMID 35054471, 2022). "Patients with severe COVID-19 often show a profound dysregulation of the immune response, as evidenced by a shift in the cytokine profile of severe COVID-19 patients towards an increase in proinflammatory cytokines such as interleukin (IL)-6, IL-8, IL-17 and macrophage inflammatory protein (MIP-1α)." (PMID 36499533, 2022). "Interleukin-6 may be a potential target in treatment of COVID-19–related cytokine storm." (PMID 36422492, 2022). "However, recombinant interleukin-6 should be decreased for patients with COVID-19." (PMID 36143492, 2022). "However, in severe COVID-19 patients, in addition to monocytes, MDSCs were able to produce IL-6 under stimulation, suggesting that they could contribute to hyper-inflammation in certain conditions." (PMID 35572540, 2022). "In particular, while recent studies examined COVID-19 associated arrhythmic risks from cardiac injury and/or from pharmacotherapy such as the combination of azithromycin (AZM) and hydroxychloroquine (HCQ), the role of IL-6 per se in increasing the arrhythmic risk remains poorly understood." (PMID 35058480, 2022).
COVID-19 (continued). "The National Institutes of Health (NIH) COVID-19 treatment guidelines panel recommends tocilizumab, an IL-6 antagonist, along with systemic corticosteroids for rapidly deteriorating COVID-19 patients and suggests through one case study that the drug may be effective for PG treatment." (PMID 35600185, 2022). "IL-6 levels could predict right ventricular systolic dysfunction in patients with COVID-19." (PMID 35524223, 2022). "In addition, a cytokine storm (triggered by interleukin-6 hyperactivation) or macrophage activation syndrome triggers systemic hyper-inflammation, thereby inducing cardiolipotoxicity and vaso-occlusive crises in patients with COVID-19." (PMID 35494937, 2022). "The interleukin-6 antagonist tocilizumab demonstrated a statistically significant but low absolute effect on mortality and progression to invasive ventilation in our meta-analysis for patients with moderate to severe COVID-19 (WHO 5–6, low to moderate quality of evidence)." (PMID 34228347, 2022). "In addition, elevated levels of IL-6 have been observed in patients with COVID-19, which may be considered to be a biomarker for predicting disease severity." (PMID 34203409, 2021). "One of the main causes of death from COVID-19 is acute respiratory distress syndrome (ARDS), and the main mechanism of ARDS is the “cytokine storm,” which is caused by immune effector cells releasing large amounts of pro-inflammatory cytokines (e.g., TNF-α, IFN-γ, IL-1β, IL-6, IL-12)." (PMID 33815131, 2021). "However, it is unclear whether IL-6 represents a marker and/or mediator of COVID-19 severe progression." (PMID 34276355, 2021). "Asthmatic patients only showed increased levels in IL-6 compared to healthy controls, suggesting that a more systemic inflammation in COPD patients might contribute to their increased risk for severe COVID-19." (PMID 34335580, 2021). "Since vit D has been shown to have immunomodulatory activity on IL-6, and anti-IL-6 agents has already demonstrated beneficial role in the course of COVID-19, it has been speculated that administration of vit D supplementation could be beneficial for COVID-19 progression." (PMID 33763085, 2021). "Hence, suppression of IL-6 may be a prime therapeutic regimen in COVID-19, as low molecular heparin is effective in management of COVID-19 through inhibition of IL-6." (PMID 34629845, 2021). "Hence, we speculate that increased IL-1β and IL-6 may worsen the disease in colorectal cancer patients with COVID-19." (PMID 34863291, 2021). "Cytokine storm due to the overproduction of proinflammatory cytokines, including interleukin (IL)-6, IL-7, IL-8, etc. in critically ill patients with COVID-19 is a critical phase of the disease that may lead to acute respiratory failure or multiple organ dysfunction." (PMID 33364433, 2021). "Furthermore, several studies have suggested IL-6 and IL-6 receptor antagonists may be of benefit in the management of critical COVID-19 patients." (PMID 34422145, 2021). "Previous studies reported that IL-6 could serve as an indicator of the progression of COVID-19." (PMID 33755708, 2021). "Hence, Nrf2 and IL-6 may be introduced as therapeutic targets for COVID-19, especially for patients suffering from inflammatory problems." (PMID 34768321, 2021). "We did not detect robust IFNγ or IL-6 expression, both of which are associated with fatal COVID-19, which may account for why the deer mice did not have significant disease or death." (PMID 34010360, 2021). "Therefore, our study supports the notion that VTE correlates with an inflammatory burst and inflammatory indexes such as LDH, IL-6 and PLR could be useful in stratifying the risk for COVID-19 patients to develop VTE manifestations." (PMID 33161478, 2021). "However, although cytokines such as IL-6 are increased in COVID-19, their serum levels are clearly lower than in Acute Respiratory Distress Syndrome (ARDS) from other causes, and lower than expected in severe cases of COVID-19." (PMID 34568275, 2021).
COVID-19 (continued). "From this observation, IL-6 inhibition may be beneficial for patients with severe COVID-19." (PMID 33557330, 2021). "Although severe COVID-19 (with ARDS) and MIS-C are two markedly different clinical entities, current immunological and pathogenic knowledge suggest that in both conditions the cytokines interleukin-1 (IL-1) and IL-6 have a pivotal role in initiating and maintaining the inflammatory response." (PMID 33947420, 2021). "Both IL-1β and IL-6 may play a role in this process, and cytokine-modulating therapies are now being tested in COVID-19 clinical trials." (PMID 33319166, 2021). "Notably, we found only dramatically elevated levels of IL-6 in severe patients compared with that in mild and moderate patients, the levels of other indicated cytokines were comparable among the three groups of COVID-19 patients." (PMID 33390771, 2021). "Moreover, IL-6 levels correlate with the severity of disease course in COVID-19." (PMID 34711233, 2021). "As a result, IL-6 may be considered as a predictive marker of COVID-19 severity." (PMID 34815399, 2021). "Moreover, ROC curve analysis suggested that IL-6 was the optimal diagnostic index to distinguish severe and nonsevere COVID-19 in patients." (PMID 34712741, 2021). "Thus, COVID-19 patients at high risk for ECMO use or in-hospital death, indicated by high levels of IL-6 and viral RNAaemia may be good targets for immunomodulation together with anti-viral agents." (PMID 34379684, 2021). "Interestingly, interleukin-6 also plays an important role in cytokine release syndrome of COVID-19." (PMID 34193201, 2021). "Therefore, the use of CT-scan along with other marks of poor COVID-19 prognosis (D-dimer, IL-6, cytokine storm, coagulopathy, comorbid conditions such as hypertension, obesity, diabetes, and advanced age) can help identify complications in patients with SARS-CoV-2 infection." (PMID 34829418, 2021). "Additionally, 17 cases developing macrophage activation syndrome (MAS) were administered tocilizumab (IL-6 antagonist) and 16 cases meeting the criteria published in the national guidelines for COVID-19 treatment in adult patients received convalescent (immune) plasma." (PMID 34099076, 2021). "Concerning SARS-CoV-2 infection, it has recently been shown that IL-6 dramatically increased in 96% of all patients investigated, suggesting that proinflammatory cytokines and therefore acute inflammation in general are major contributors to the altered lipid metabolism in COVID-19 patients." (PMID 34440605, 2021). "COVID-19 is accompanied by the activation of the immune system and the elevation of inflammatory cytokines, such as C-reactive protein, ferritin, and interleukin-6 (IL-6), and could induce a severe catastrophe response with hyperinflammation, namely, the “cytokine storm”." (PMID 34623311, 2021). "The effect of IL-6 itself on the pathogenesis of COVID-19 may be complex." (PMID 35095877, 2021). "Previously, the inflammatory biomarkers (IL-6, IL-8, IL-10 and ratio of IL-6 to IL-10), patients’ characteristics (age) and chest CT images (consolidation, emphysema and residual healthy lung parenchyma) have been reported to predict the prognosis of COVID-19 patients." (PMID 34217339, 2021). "The studies have shown that Bufei Huoxue Capsule could effectively improve pulmonary fibrosis, reduce the expression of inflammatory factors such as TNF-α and IL6, promote lung tissue repair, and effectively improve the immune response, which also contributes to the recovery of COVID-19." (PMID 34335247, 2021). "Research of IL-6 inducing peptides/epitopes may shine lights on COVID-19 vaccine development." (PMID 37287491, 2021). "Similarly, clinical trials for the IL-1α/β blockers Anakinra and Canakinumab have shown promise in improving COVID-19 outcomes, while the IL-6 antagonist Tocilizumab is approved by the FDA under an emergency use authorization for combination use with dexamethasone for added benefit." (PMID 34777390, 2021).
COVID-19 (continued). "For example, Diagnosis and Treatment Protocol of COVID-19 (Trial Version 7) released on 4 March 2020 specifies clinical early-warning indicators of severe and critical cases for the first time; these indicators include cytokines, interleukin 6, and C-reactive protein." (PMID 34488797, 2021). "Given that overproduction of plasma IL-6 levels was observed in patients with severe COVID-19, and also in patients with disseminated malignancies, it is conceivable that IL-6, or its downstream molecules, could be a promising target for the treatment of COVID-19." (PMID 34001144, 2021). "The high circulating level of IL-6 released in COVID-19-infected patients with smoking-related cancers might indicate an host immune inbalance, resulting in an exaggerated immune response and hyperinflammation with a cytokine storm syndrome and severe evolution." (PMID 33216184, 2021). "Therefore, the COVID-19-muscle-IL-6 triangle is also worth investigating." (PMID 33763027, 2021). "Furthermore, increased release of cytokines like interleukin-6 in patients with diabetes and COVID-19, in the face of possible blunted antiviral interferon responses and the delayed activation of Th1/Th17, may contribute to worse outcomes." (PMID 34143791, 2021). "In summary the study showed that plasma concentrations of HMGB1 and IL-6 assessed at ICU admission could accurately identify COVID-19 patients with a fatal outcome of the disease, with a predictive precision similar to or better than the SOFA or the COVID-GRAM risk scores." (PMID 33939645, 2021). "In this scenario, high levels of interleukins (IL), notably IL-6 and IL-1, create a positive feedback of chemokines and immune responses, and powers pulmonary and systemic tissue damage, leading to capillary leakage and SARS, the main cause of death in patients with COVID-19." (PMID 33008960, 2021). "Thus, the inhibition of IL-6 is hypothesized to be a promising therapeutic strategy to interfere with COVID-19-induced cytokine storm and thereby alter the course of disease progression." (PMID 34001244, 2021). "However, further and repeated study with larger datasets, after stratifying for COVID-19 severity and/or serum cytokine expression levels, would be justified in considering miR-766-3p aw key molecule in this inflammatory event mediated directly by IL-6 in CSS." (PMID 34564316, 2021). "Besides CAR-T-induced CRS in adults and children, many studies also showed that the serum of IL-6 increased remarkably in patients with COVID-19.147–149 Besides, targeting IL-6 pathway has led to innovative therapeutic approaches for various rheumatic diseases and related therapy is on the way." (PMID 34667157, 2021). "IL-6 inhibitor and Janus kinase inhibitors may also improve the clinical outcomes of COVID-19." (PMID 34440608, 2021). "Also, the Chinese COVID-19 diagnosis and treatment plan (trial version 8) recommended dropping lymphocytes, rising inflammatory factors (e.g., IL-6, CRP), increasing LDH and rapidly progressive pulmonary changes are the predictive factors for severe and critical COVID-19." (PMID 33588779, 2021). "Also, that IL-6 levels are increased in some asthmatic patients (especially in females) and this may influence their response to COVID-19." (PMID 34335580, 2021). "Whether the IL-6 level rather than blood pressure is the independent variable determining COVID-19 severity risk is unresolved." (PMID 34441038, 2021). "In addition, in the single patient with COVID-19 but without loss of smell, no cell death or immune cells were observed in the olfactory mucosa, but IL-6 was elevated." (PMID 33941622, 2021). "We believe that the results of our review and meta-analysis including a relevant number of patients, especially those related to IL-6 and ferritin, can be extrapolated to the real world, supporting clinical practice in coping with COVID-19 and may help decision-making processes." (PMID 34185801, 2021). "Additionally, IL-6 levels predict severity in COVID-19 patients." (PMID 33397150, 2021).
COVID-19 (continued). "Moreover, R. crenulata might play an anti-inflammatory and immunoregulatory role in the cytokine storm of COVID-19 by acting on IL-1β, IL-6 and TNF-α." (PMID 34313585, 2021). "Thus, IL-6 represents a common biomarker for COVID-19 and AD." (PMID 33673697, 2021). "Therefore, sgp130Fc is expected to be a potential inhibitor of IL-6 in COVID-19 patients because it can retain the regenerative and anti-inflammatory properties of the IL-6 classic pathway and only block the proinflammatory effects mediated by the trans-signaling pathway." (PMID 33628091, 2021). "Moreover, inhalation of welding fumes (mainly containing zinc) both increases pneumonia and cardiovascular risk and induces fever, fatigue, muscle ache, cough, dyspnoea, and a cytokine storm including IL-6 and IL-10, thus resembling the symptoms observed in COVID-19 patients." (PMID 33673459, 2021). "In addition, studies have shown that c-reactive protein (CRP), interleukin-6(IL-6), D-dimer and hepatic cytokines (HGF) and C-X-C motif chemokine 13 (CXCL13) are associated with the occurrence of pulmonary fibrosis in patients with COVID-19." (PMID 35069217, 2021). "Moreover, antidepressant use has been associated with a reduced risk of intubation or death in hospitalized patients with COVID-19 because the inhibition of ASM decreases pro-inflammatory mediators such as IL-2, IL-6, IL-7, IL-10, TNF-α, C-reactive protein (CRP), and D-dimer." (PMID 34579284, 2021). "Indeed, the interplay between IL-6, its cellular source and specific chemokines recruiting these latter are all mandatory and limiting steps required for the initiation and perpetuation of the CS of COVID-19." (PMID 33981314, 2021). "However, unlike adult cases of COVID-19, IL-6 has not been directly associated with severity, and we were not able to demonstrate a higher IL-6 in MIS-C patients with shock." (PMID 34869111, 2021). "Finally, In the international, multifactorial, adaptive platform trial REMAP-CAP (NCT02735707), both tocilizumab and sarilumab (another IL-6 inhibitor), met predefined criteria for efficacy against COVID-19 in critically ill patients receiving organ support in ICU." (PMID 34006330, 2021). "Since high levels of the cytokine IL-6 are found in COVID-19 patients and the promotor of zonulin is under control of this cytokine, the overexpression of zonulin in the brain could also be related to the presence of IL-6 in the brain capillaries." (PMID 33981312, 2021). "However, whether IL-6 is detrimental or beneficial in COVID-19 remains unclear and is highly probable that timing is the most important factor in determining the success or not of anti-IL-6 treatments." (PMID 33717168, 2021). "Finally, increased IL-17 production by Th17 cells in COVID-19 patients has broad pro-inflammatory effects through the upregulation of pro-inflammatory cytokines like G-CSF, IL-1β, IL-6, TNFα, as well as chemokines like MIP2A, IL-8, IP10, MIP3A, and matrix metalloproteinases." (PMID 34512643, 2021). "His symptoms worsened in the absence of evidence for bacterial or fungal infection; therefore, he was considered to have developed sHLH due to an uncontrolled cytokine storm caused by COVID-19, although his serum IL-6 levels were not determined after the development of sHLH." (PMID 33011959, 2021). "IL-6 and other immune mediators might play a dual role in the pathogenesis of COVID-19." (PMID 33216184, 2021). "Therefore, hyponatremia might be used to identify the subgroup of COVID-19 patients who might benefit from targeted therapeutic approaches, such as IL-6 antagonists." (PMID 33624101, 2021). "In addition, targeting IL-6 may ameliorate the cytokine storm-related symptoms in severe COVID-19 cases." (PMID 33811756, 2021).